Y_RNA (Y RNA )
Gene: Miscellaneous RNA gene on chromosome 5 (140,019,492 to 140,019,592, forward strand). Ensembl gene ENSG00000207317.
Homologues: Orthologues: chimpanzee Y_RNA (99% identical), macaque Y_RNA (91% identical). Paralogues in human: Y_RNA (87% identical), RNY3 (86% identical), Y_RNA (86% identical), Y_RNA (85% identical), Y_RNA (84% identical), RNY3P1 (83% identical), Y_RNA (83% identical), RNY3P14 (82% identical), Y_RNA (82% identical), RNY3P10 (81% identical), RNY3P4 (81% identical), Y_RNA (81% identical), and 93 more.